GFI1B (growth factor independent 1B transcriptional repressor)
Diseases named in the same sentence as GFI1B in open-access papers (continued):
Sharing a sentence is not in itself a finding about the gene and the disease.
Hypertension (1 paper, 2024). The presence of chronic increased pressure in the systemic arterial system. "Three machine learning algorithms identified five biomarkers associated with hypertension: calmodulin 3 (CALM3), cluster of differentiation 9 (CD9), growth factor independence 1B transcriptional repressor (GFI1B), myosin light chain kinase (MYLK), and Ras suppressor-1 (RSU1)." (PMID 39519602, 2024). "Given the elevated expression of GFI1B, MYLK, and RSU1 in hypertension, we performed GSEA to focus on their functional enrichment in this context." (PMID 39519602, 2024). "We previously discussed the relationship between GFI1B, MYLK, and RSU1 and hypertension, noting their roles in vascular resistance and renal metabolic pathways." (PMID 39519602, 2024). "The intersection of the three machine learning algorithms identified five genes as potential key biomarkers for hypertension: calmodulin 3 (CLAM3), CD9, growth factor independent 1B transcriptional repressor (GFI1B), myosin light chain kinase (MYLK), and Ras Suppressor Protein 1 (RSU1)." (PMID 39519602, 2024). "Although no direct evidence links GFI1B to blood pressure fluctuations, we hypothesize that it may regulate RAS activation via the Wnt/β-catenin pathway, leading to hypertension." (PMID 39519602, 2024).
tumor (7 papers, 2013 to 2023). "MAPK inhibition in NKX2-1-negative tumor cells was also associated with induction of several markers of chemosensory tuft cells, including the lineage specifier Pou2f3 as well as Gfi1b and Gnat3." (PMID 33821796, 2021). "Similarly, loss of heterozygosity leading to low expression of GFI1B was also associated with myeloid leukemic transformation, suggesting that at normal level in early myeloid progenitors, GFI1B may act as a tumor suppressor, possibly by driving differentiation toward the erythroid lineage." (PMID 33193732, 2020). "It has been reported that Gfi1b down-regulates Gata3 expression in tumor cells." (PMID 24098325, 2013). "Thus, in this setting GFI1B functions also as a tumor suppressor." (PMID 31649884, 2019). "CDCA7, CELSR3, PACS1, SNTB1, and TBC1D31 showed consistent upregulation in CRC tumor samples and pre-surgical cfRNA, while GFI1B, HPGD, SH3BGRL2, SIAE, PKHD1L1, and TDP2 showed downregulation in CRC tumor samples and pre-surgical cfRNA." (PMID 37091184, 2023).
cancer (5 papers, 2015 to 2022). A tumor composed of atypical neoplastic, often pleomorphic cells that invade other tissues. "In most cases, GFI1B/GFI1 mutually exclusive abnormal expression was produced by structural variants, showing that abnormal expression of GFI1B is definitely linked with human cancer." (PMID 28401061, 2017). "In keeping with this key role in cell fate, GFI1B is emerging as a gene involved in cancer, which also includes solid tumors." (PMID 28401061, 2017). "GSK-LSD1 is also tranylcypromine-based and is classified as a catalytic inhibitor of LSD1; however, recent work finds its anti-cancer effect is primarily due to allosteric disruption of the LSD1 interaction with AML oncoprotein Growth Factor Independent 1B (GFI1B)." (PMID 35687133, 2022). "However, more data will be needed to get a full insight into the mechanisms involved in GFI1B’s role in cancer, particularly in the blood setting and the importance of its two isoforms." (PMID 28401061, 2017). "SOX2 has been implicated in growth, tumorigenicity, drug resistance, and metastasis in at least 25 different cancers, TARDBP is involved in apoptosis and cell division, while GFI1B positively regulates c-Myc expression and increases the proliferation rate of cancer cells." (PMID 29950180, 2018).
infection (2 papers, 2022 to 2025). The state of being infected such as from the introduction of a foreign agent such as serum, vaccine, antigenic substance or organism. "Here, infection with O. ostertagi induced the expression of some Tuft cell markers, including POU2F3, CHAT, TRPM5, and GFI1B in cattle." (PMID 40076885, 2025).
blood cancer (1 paper, 2017). "Therefore, the major role of GFI1B in hematopoiesis makes it a good candidate to be involved in blood cancers." (PMID 28401061, 2017).
GFI1B also shares sentences with these, for which no sentence is quoted: blood disease (2 papers); acute erythroid leukemia (1); acute lymphoblastic leukemia (1); acute megakaryoblastic leukemia (1); adenocarcinoma (1); blood disorders (1); breast carcinoma (1); cholestasis (1); colitis (1); COVID-19 (1); megakaryoblastic leukemia (1); myeloproliferative neoplasm (1); Obesity (1); osteosarcoma (1); renal dysfunction (1); small cell lung carcinoma (1).